CRP (C-reactive protein)
Diseases named in the same sentence as CRP in open-access papers (continued):
Sharing a sentence is not in itself a finding about the gene and the disease.
Obesity (continued). "Among the importance of predictor variables for end-stage KOA comorbidity, anxiety was the most important with a value of 1.0, followed by obesity (0.81), ultrasensitive C-reactive protein (0.70), depression (0.66), blood sedimentation (0.59), BMI (0.58) and rheumatoid arthritis (0.54)." (PMID 38627663, 2024). "First, obesity may lead to elevated levels of inflammatory cytokines such as tumor necrosis factor-α, interleukin-6, and C-reactive protein." (PMID 38577567, 2024). "GCE significantly decreased the hs-CRP levels in patients with T2D and overweight/obesity." (PMID 39065815, 2024). "The low-grade inflammatory response triggered by diet and obesity involved numerous biomarkers, including circulating (i.e., C-reactive protein [CRP]) and cellular (i.e., leukocyte count) which were found to be relevant to increased risks of chronic diseases as well." (PMID 39064755, 2024). "Obesity leads to the accumulation of lipids in adipocytes and is responsible for triggering the release of inflammatory markers such as tumor necrosis factor-α (TNFα), interleukin-6 (IL-6), and C-reactive protein (CRP) and for insulin resistance." (PMID 39759127, 2024). "Notably, Prevotella exhibited a positive correlation with hs-CRP and showed a significant increase in individuals with obesity, indicating potential implications for systemic disease outcomes." (PMID 39200519, 2024). "Malnutrition weakens the immune system, reducing essential immune cells like T lymphocytes and impairing antibody production, while overnutrition and obesity result in chronic low-grade inflammation, elevating inflammatory markers such as C-reactive protein (CRP) and interleukin-6 (IL-6)." (PMID 39201314, 2024). "However, BMI, waist circumference, hip circumference, waist/hip ratio, systolic blood pressure, total cholesterol, LDL-cholesterol and C-reactive protein were significantly higher in subjects with obesity." (PMID 38541185, 2024). "Further analyses revealed that increased CRP levels were also associated with light DIY activities, walking for pleasure, and television watching, although these associations became less robust after controlling for obesity-related confounders." (PMID 39088575, 2024). "In addition, CRP can increase for a variety of reasons (e.g., chronic stress, chronic disease, virus, or obesity)." (PMID 38339813, 2024). "In addition, overweightness and obesity in children have been associated with elevated IL-6, CRP, and MCP-1, and CRP has been positively correlated with MCP-1, IL-6, and IL-10." (PMID 38396489, 2024). "Furthermore, observational studies have revealed a higher prevalence and incidence of common CVD risk factors, such as diabetes mullites, dyslipidemia, arterial hypertension, obesity, smoking, alcohol consumption, and CRP, in psoriasis patients." (PMID 39200903, 2024). "Thus, while ACPA-positive RA patients with obesity had higher CRP levels over time compared to normal weight RA patients, this did not apply to ACPA-negative RA patients." (PMID 38321544, 2024). "We used Cox regression to estimate hazard ratios (HRs) with 95% confidence intervals (95% CIs) to compare outcomes across CRP quartiles, overall and stratified by BMI (normal-weight (18.5 ≤ BMI < 25 kg/m2), overweight (25 ≤ BMI < 30 kg/m2), and obesity (BMI ≥ 30 kg/m2))." (PMID 38914635, 2024). "Our data-driven approach not only uncovers a causal relationship from obesity to HTN, body inflammation (assessed by CRP levels), and insulin resistance (HOMA-IR), but also provides further evidence that obesity significantly increases the risk of developing these conditions." (PMID 39717478, 2024). "Both girls and boys with overweight or obesity showed higher CRP levels." (PMID 39857642, 2024).
Obesity (continued). "Previous studies have reported the association between AKI and several factors including anemia, preoperative serum creatinine, higher age, heart disease, comorbidities, obesity, hypoalbuminemia, blood transfusion and C-reactive protein; however, there was some discrepancy between reports." (PMID 38792928, 2024). "Compared with Chinese, Malays and Indians had significantly lower SES, poorer systemic profile including, higher CRP, obesity, DM, HTN, IHD, CKD, and polypharmacy, a higher proportion of them were current smokers and alcohol consumers, were physically less active, and had lower caloric intake." (PMID 38646827, 2024). "Both boys and girls with overweight or obesity had significantly higher CRP levels." (PMID 39857642, 2024). "The negative associations of dietary calcium with fasting glucose levels and markers of chronic inflammation such as C-reactive protein (CRP) may explain the protective role of calcium in obesity pathogenesis." (PMID 38540656, 2024). "Obesity and overweightness are well-known proinflammatory metabolic disorders relating to high levels of inflammatory markers including interleukin (IL-)1β, IL-6, C-reactive protein, and tumor necrosis factor (TNF)α." (PMID 39337202, 2024). "Molecular markers of obesity (e.g., IL-6, CRP, IL-1 β) increase the generation of MDSCs." (PMID 39399429, 2024). "To investigate the effects of primary mechanisms of obesity-induced cancer on HCC risk, we initially included a total of 263 SNPs as IVs associated with C-reactive protein levels, 6 SNPs with circulating leptin levels, 14 SNPs with adiponectin, 9 SNPs with severe insulin-resistant type 2 diabetes." (PMID 38977823, 2024). "Our findings are consistent with studies suggesting that routine markers such as total leukocyte count and CRP may reliably reflect inflammation in children and adolescents with obesity." (PMID 39857642, 2024). "It was found that CRP and IL-6 increased with obesity-related traits." (PMID 39337223, 2024). "Moreover, obesity results in elevated levels of leptin and inflammatoryindicators like C-reactive protein (CRP), exacerbating vascular and myocardialdamage." (PMID 39742220, 2024). "By contrast, the results of other authors indicate obesity further increases CRP levels, which may indicate chronic inflammation." (PMID 39518325, 2024). "Trends included a positive association of HS C-reactive Protein and insulin and obesity as well as a negative association between blood lead level and blood cadmium level and obesity." (PMID 38820332, 2024). "CRP, an acute-phase protein, is released in response to inflammation triggered by IL-6 secretion and is considered an additional marker of metabolic syndrome, with elevated levels often seen in obesity and insulin resistance." (PMID 39468643, 2024). "As ACPA is suggested to enhance inflammatory responses, we hypothesized that the association of obesity with SJC and CRP is present especially in ACPA-positive RA." (PMID 38321544, 2024). "In addition, there was a considerable decrease in serum levels of CRP among both healthy and unhealthy participants with obesity and baseline CRP levels >3 mg/L over long-term supplementation with high doses of SIL." (PMID 38671838, 2024). "The higher level of ln‐CRP, the higher the proportion of females, non‐Hispanic Black, education level less than high school, divorced or widowed or separated, obesity, physically inactive, former alcohol user, smoking now, CVD, DM, hypertension, and stroke (p < .05)." (PMID 39222043, 2024). "Obesity was associated with higher age, a higher prevalence of non-Hispanic Black, no college education, Income poverty, elevated SF and sTfR, reduced MCV and MCHC, elevated prevalence of anemia and increased incidence of elevated CRP or HsCRP." (PMID 38544758, 2024). "By lowering inflammatory markers such as C-reactive protein (CRP), statins may alleviate chronic inflammation, a key driver of renal injury in obesity." (PMID 39765868, 2024).
Obesity (continued). "Elevated CRP levels in obesity may contribute to the development of periodontitis, which, along with other inflammatory and environmental factors, can lead to tooth loss or, in severe cases, complete loss of dentition." (PMID 39563168, 2024). "Insulin resistance and adipocyte proliferation caused by obesity lead to the secretion of inflammatory mediators by adipocytes, such as Interleukin-6 (IL-6), Tumor Necrosis Factor-alpha (TNF-α), and C-reactive protein (CRP)." (PMID 38933362, 2024). "This may be due to the opposing directions of the direct effect and the indirect effect mediated by CRP, which could suppress the influence of the snack pattern on obesity." (PMID 39599620, 2024). "A graded relation between elevated CRP percentage and obesity was observed in both women and men." (PMID 38544758, 2024). "Regarding tissue inflammation as a result of obesity, There was a significant elevation (P<0.001) in serum CRP in group III and group VI compared to group I and group II, chia seeds ingestion significantly (P<0.01) reduced these levels in group IV compared to the group III." (PMID 38316807, 2024). "The effect of obesity (p < 0.006), smoking (p < 0.001) and alcohol consumption (p < 0.001) on RvE1 remained significant after further adjusting for the inflammatory markers hs-CRP and leukocyte count." (PMID 38347128, 2024). "Overweight or obesity is associated with high blood pressure, insulin resistance, and high C-reactive protein and lipid levels in Chinese adolescents, independent of risk factors for type 2 diabetes, metabolic syndrome, and other complications in later life." (PMID 38596795, 2024). "Obesity is a low-grade inflammation characterized by increased production and secretion of inflammatory cytokines, such as interleukin-6 and tumor necrosis factor-α, which stimulate the liver to synthesize and release CRP into circulation." (PMID 39765954, 2024). "Additionally, the positive correlation between BMI and CRP, respectively, and leptin levels suggest a link between obesity and inflammation." (PMID 39768291, 2024). "Our results indicate the link between 5-mC and CRP levels, which may prove relevant in differentiation of obesity grades." (PMID 39057082, 2024). "In addition, chronic systemic inflammation is recognized as part of insulin resistance syndrome, T2DM, and obesity and is characterized by increased IL-6 and CRP levels, as well as decreased levels of adiponectin (ADIPOQ) and IL-10." (PMID 39408723, 2024). "The pathophysiology linking obesity and elevated CRP levels has been widely discussed." (PMID 37754594, 2023). "Furthermore, a relatively recent study showed that in obesity, the monomeric form of CRP binds to leptin receptor." (PMID 37873776, 2023). "Significant differences of CRP levels were observed between normal-weight and obese patients (1st FU: pnormal weight vs. obesity = 0.02; 2nd FU: pnormal weight vs. obesity < 0.01; 3rd FU pnormal weight vs. obesity = 0.02)." (PMID 37885885, 2023). "Overall, these results suggest a potentially important role of immunity in determining the interactions between depression, obesity, and HTG on their association with RA; however, the nature of such interactions is not well understood from the current results based on CRP." (PMID 38455932, 2023). "For example, when depression and obesity were considered at the medium CRP range, the prevalence of RA in subjects with depression and obesity were 19.5% and 5.5%, respectively; however, RA prevalence increased to 27.2% for the population with both depression and obesity." (PMID 38455932, 2023). "In a study with hypertensive and/or diabetic patients with obesity and high levels of inflammatory markers, AA supplementation significantly reduced the concentrations of C-reactive protein (CRP), IL-6, fasting blood glucose, and triglyceride in blood than the AA-untreated group." (PMID 37428327, 2023).
Obesity (continued). "Studies based on the interaction between serum proteins and leptin show that human CRP directly inhibits the binding of leptin to the receptor in vitro and blocks the signaling pathway of leptin, which suggests that CRP can promote obesity and metabolic complications." (PMID 37893085, 2023). "The decline in Cu levels may be as a result of reducing CRP levels and resolution of the pro-inflammatory obesity state following bariatric surgery." (PMID 37773088, 2023). "Similarly, positive correlations were found between hs-CRP levels and all obesity markers analyzed in the study." (PMID 37375693, 2023). "In detail, studies revealed that early AFB (younger than 20 years) was associated with several cardiovascular factors by mid-life, including body mass index, obesity, blood pressure, cholesterol, triglycerides, glycated haemoglobin, C reactive protein, von Willebrand factor, and fibrinogen." (PMID 37024926, 2023). "This sustained inflammatory status modulated by obesity could play a central role in clinical disease activity through a positive feedback loop with pro-inflammatory mediators, such as CRP." (PMID 36839394, 2023). "The study suggests that the fiber amount for hypertensive subjects with obesity may need to be increased, or the CRP-lowering effect of fiber may be more effective if combined with other treatments for those with insulin resistance and metabolic syndrome." (PMID 37702886, 2023). "Obesity status was correlated with elevated CRP in FRA in previous BRINDA analyses." (PMID 36789936, 2023). "In the current literature, male sex, obesity, chronic kidney disease, benign prostate hyperplasia, elevated serum C-reactive protein (CRP), and revision for adverse metal reaction and component loosening are discussed as possible risk factors for finding UPCs or subsequent revision for PJI." (PMID 37175046, 2023). "The aims of this study were to examine the effect of obesity on the association between peripheral blood and GCF CRP levels and to examine the association between GCF CRP and GCF inflammatory cytokines in periodontally healthy obese individuals without the confounding effect of periodontal disease." (PMID 38138192, 2023). "Therefore, abnormal levels of both need to be interpreted with caution as the inflammatory nature of the obesity condition, and hence, elevated CRP levels impact the serum levels of these." (PMID 37773088, 2023). "Second, the level of CRP is higher in children with obesity, and chronic inflammation is a characteristic of obesity, as adipocytes trigger metabolic signals that induce inflammation as indexed by increases in the levels of CRP and other inflammatory markers such as IL6 with disruption of sleep." (PMID 37305117, 2023). "For example, patient obesity, fat distribution, smoking status, some comorbidities, age or sex, leukocyte count, C reactive protein (CRP) value, and heart rate are considered predictors by some authors, while other studies did not validate them as being of relevance." (PMID 37834836, 2023). "Obesity was related to increased concentrations of CRP, not only in adults but also in children." (PMID 37242271, 2023). "Adiposity development may be a key element in the generation of CRP and systemic inflammation that led to obesity." (PMID 37237937, 2023). "Furthermore, for obesity, the effect was more prominent for the subjects in the low and medium CRP group, while for depression, a stronger effect was observed in the medium or high CRP group." (PMID 38455932, 2023). "As serum CRP and obesity are important predictors of cardiovascular risks in clinics, our observations suggest taking rare genetic factors into consideration might improve the delivery of precision medicine." (PMID 37493001, 2023). "Obesity is considered a chronic inflammatory condition as evidenced by the increased immune cell infiltration of adipose tissue with excess production of circulating proinflammatory factors, including cytokines and C-reactive protein (CRP)." (PMID 37446154, 2023).
Obesity (continued). "Our finding suggests an effect or a link between CRP with obesity in women with GDM." (PMID 37891561, 2023). "On the other hand, ACBP was not independently associated with markers of obesity, glucose homeostasis, and dyslipidemia in multivariate linear regression analysis in the entire cohort nor with CRP when included instead of hsIL-6 (Model 2)." (PMID 37288304, 2023). "Groups with obesity had greater CRP levels than the NH-NO group." (PMID 36725863, 2023). "Hs-CRP and WBC were positively associated with obesity and central obesity, respectively." (PMID 36900791, 2023). "One viable pathway via which adiposity may influence strength involves the obesity-related state of chronic low-grade inflammation, as indicated by inflammatory markers including C-reactive protein (CRP)." (PMID 37803197, 2023). "However, conventional methods of CRP analysis were found to be more accurate in differentiating between children and adolescents with obesity and those with MetS, compared with hsCRP (MD = 0.60, 95% CI: (−0.08–1.28), p = 0.08)." (PMID 38001962, 2023). "Another limitation was the nature of our study design, which did not allow the assessment of cause-effect relationships between selected measures of obesity (BMI, WC, RFM, VAI, WHtR) and parameters of chronic inflammation (CRP, TNF-α, IL-6) in perimenopausal healthy women." (PMID 37375693, 2023). "A total of 549 (38.26%) participants with obesity had CRP levels ranging between 3 and 10 mg/L." (PMID 36462595, 2023). "However, significant decreases in serum TNF-α and CRP were observed after a 10-week lifestyle intervention conducted with 23 children and adolescents with obesity." (PMID 38063544, 2023). "In our study, IL-8 was the only cytokine that tended to show a strong association with GCF CRP in the obese subjects, suggesting that IL-8 production in gingival tissues is not weakened by obesity." (PMID 38138192, 2023). "Furthermore, HTG was found to decrease the prevalence of RA among subjects with obesity at low CRP level and subjects with depression at high CRP level." (PMID 38455932, 2023). "Obesity-related increased levels of CRP in gingival tissues may provide insightful information about how obesity affects periodontal health." (PMID 38138192, 2023). "The comorbidity of depression with obesity and metabolic dysregulation is thought to be related to chronic low-grade inflammation, characterized by increased circulating levels of pro-inflammatory cytokines and C-reactive protein (CRP)." (PMID 37373992, 2023). "A recent systemic review highlighted improvements in inflammatory biomarkers in adults with obesity using aerobic exercise training (decreased CRP, IL-6, and TNF-α), resistance training (decreased TNF-α), and concurrent training including both aerobic and resistance training (decreased TNF-α)." (PMID 37372149, 2023). "Disruption of leptin-CRP and the interaction between CRP and leptin receptors may be a target for the treatment of obesity and obesity-related NAFLD." (PMID 37893085, 2023). "Congruent with past research, statistical adjustment for BMI in the multivariate analysis affected the strength of associations between the inflammatory marker and symptom dimensions of MDD, probably due to the confounding effect of obesity, which is moderately correlated with CRP." (PMID 36831896, 2023). "In one study of 109 consecutive patients with obesity (mean BMI 46.6 ± 7 kg/m2), 18% were classified as hypercoagulable based on rotational thrombelastometry, and these patients had increased levels of C-reactive protein, fibrinogen, and platelets compared with the other patients." (PMID 37396589, 2023). "CRP is an acute phase plasma protein synthesized in the liver in response to inflammatory cytokines and chemokines and, therefore, it is regarded as a surrogate marker of inflammatory conditions including obesity, metabolic syndrome, and atherosclerosis." (PMID 37894865, 2023).